IL6 (interleukin 6)
Diseases named in the same sentence as IL6 in open-access papers (continued):
Sharing a sentence is not in itself a finding about the gene and the disease.
infection (continued). "IL-6 is a versatile pleiotropic cytokine that regulates immune response, acute phase response, and hematopoiesis, and plays an important role in the body’s anti-infection immune response." (PMID 34210334, 2021). "IL-6 secretion occurs within two hours following onset of infection." (PMID 34205852, 2021). "In addition, we assess the post-traumatic infections by biomarkers of post-traumatic inflammation IL-6, IL-10, CRP, and WBC." (PMID 34568354, 2021). "Infection can stimulate the expression of pro-inflammatory genes, such as IL-6, TNF-α, etc., which can effectively eliminate microorganisms, accelerate tissue repair, and secret IL-10 and other anti-inflammatory cytokines to alleviate the inflammatory reaction." (PMID 33868293, 2021). "Besides, IL-6 is involved in the metabolism of iron by inducing hepcidin which decreases iron absorption, to make a microenvironment prohibitive against infection." (PMID 34803441, 2021). "When an organism is under injury, infection, and inflammation, the activated monocytes and injury tissue can secret pro-inflammatory cytokines, such as interleukin-1 (IL-1), interleukin-6 (IL-6), and tumor necrosis factor (TNF-α), which can induce the secretion of APPs." (PMID 34941838, 2021). "The cytokine storm starts with the release of IL-6 upon infection with SARS-CoV-2." (PMID 34205852, 2021). "After infection, the levels of IL-6, IFN-γ and TNF-α on days 4 and 7 in the untreated group were significantly increased (P < 0.01), and treatment with loperamide and GOS could inhibit the secretion of IFN-γ and TNF-α." (PMID 33676495, 2021). "Corroborating previous reports demonstrating that IL-6 is often correlated with the susceptibility to infection in several bacterial models, we demonstrated that IL-6 is required for the control of Brucella replication in vivo during the early phase of the infection." (PMID 33322581, 2020). "Here we explore the idea that an exacerbated inflammatory response, in particular that mediated by IL-6, may drive the deleterious consequences of the infection." (PMID 32276453, 2020). "Acute T. cruzi experimental infection in mice with high inoculum, in fact, was followed by increased IL-6, high parasite load in tissue and marked inflammation while IL6-KO mice developed different levels of parasite load in the blood and myocardium depending on the T. cruzi strain." (PMID 33193300, 2020). "In addition, treatment of macrophages with 2-DG or the use of glucose-deprived media impaired the production of proinflammatory cytokines, including IL-1β, TNF, and IL-6, after 24 h of infection." (PMID 32385235, 2020). "Similarly, we observed an increase in IL-6 and IL-8 protein levels in endothelial supernatant 24 hr post-infection." (PMID 32697191, 2020). "Strikingly, even systemic C. jejuni induced pro-inflammatory cytokine responses were dependent on an intact pepP gene, given that IFN-γ, TNF, MCP-1, and IL-6 concentrations were lower in serum samples following ΔpepP versus WT and pepP complemented strain infection (p < .05–0.01)." (PMID 32584649, 2020). "We argue that evaluation of immune parameters in COVID19 patients need to first be studied to ensure that IL-6 is involved in immunopathology and second to determine at what level or time point in the clinical course of infection, IL-6 produces immunopathology." (PMID 33051534, 2020). "During infection, key mammalian innate immune response factors (e.g., interferon gamma, tumor necrosis factor alpha, interleukin 1 [IL-1], and IL-6) have evolved to modulate iron metabolism in order to inhibit overall iron release and thus starve invading pathogens for the molecule." (PMID 32699121, 2020). "Additionally, to form the inflammatory microenvironment, the immune response is initiated to activate the releasing of pro-inflammatory cytokines such as IL-1β and IL-6 when damage and infection occur." (PMID 33375269, 2020).
infection (continued). "Furthermore, IL-6 levels in the early phase of infection were also elevated in bleeding patients with plasma leakage." (PMID 32124729, 2020). "However, in a subgroup analysis in patients with severe and critical disease, we found a substantial tendency toward an increased rate of secondary infections owing to anti-IL-6 signaling treatment in the critical group." (PMID 33384605, 2020). "Besides IL-6, IL-8 is an important cytokine that activates chemotaxis in neutrophils and granulocytes, which then migrate toward the infection site." (PMID 32111037, 2020). "C-reactive protein is an acute-phase reactant protein which is synthesized mainly by hepatocytes but also by blood monocytes in response to infection or inflammation upon stimulation by proinflammatory cytokines as interleukin-6 (Il-6) and tumor necrosis factor-α (TNF-α)." (PMID 32307587, 2020). "Cemip−/− mice studied here had greater IL-6 and neutrophil infiltration, a reaction that may have helped fight infection." (PMID 31914398, 2020). "IL-6 expression was significantly increased after TLT2 overexpression followed by H37Rv infection." (PMID 33042115, 2020). "A more focused investigation of infection-specific markers IL-1α, IL-1β, IL-6, IL-8, MCP-1, MIP-1α, and MIP-1β could provide insight into the power of these cytokines to discriminate aseptic vs. septic tissues." (PMID 32867801, 2020). "We found that 11g-treated C. albicans could increase the secretion of TNF-α, IL-10, IL-12/23 p40, and IL-6 in macrophages after 6 h post-infection." (PMID 32695076, 2020). "MAYV infection induced acute production of several pro-inflammatory molecules in the spleen such as IL1-β and IL-6 from days 1 to 7 of infection; IFN-γ from days 1 to 5 and finally, TNF-α at the early time-points of 1 and 3 days post-MAYV inoculation." (PMID 32210270, 2020). "Moreover, when evaluating DCs obtained from a mouse with a silenced TLR4 and infected with hMPV, the cytokines induced by the infection, such as IL-6, IL-10, CCL5, and IFN-β, were also decreased." (PMID 32765522, 2020). "IL-6 production can be induced by both infection and other types of inflammation." (PMID 32718086, 2020). "Furthermore, EgCME-E-I159V infection significantly increased the expression levels of the genes encoding interferon (IFNβ) and factors related to antibody and inflammatory responses (IL6 and TNFα, respectively) as compared with EgCME-WT infection." (PMID 32346055, 2020). "A recent study showed a systemic up-regulation of IL-6 during the acute phase of infection." (PMID 33244370, 2020). "Pretreatment of primary cultures of human nasal and tracheal epithelial cells with glycopyrronium or formoterol decreased viral RNA levels and/or titers, the expression of the HCoV-229E and the infection-induced production of cytokines, including IL-6, IL-8 and IFN-beta." (PMID 32256705, 2020). "Moreover, the expression of IL-6 was lower in DAPT-treated cells prior to infection (1.3 ± 0.13), and post-infection (1.3 ± 0.04) compared to MAP-untreated infected cells (1.8 ± 0.18) (p < 0.05)." (PMID 32635645, 2020). "The correlation with markers of infection and inflammation has been confirmed by others, with lower plasma glutamine levels found to be associated with lower albumin levels, higher CRP levels, and higher circulating IL-1β and IL-6 levels." (PMID 32028696, 2020). "WT and CD200R1 PCLS showed a similar IL6 induction upon infection with live or heat-killed CHA." (PMID 33250899, 2020). "Therefore, one of the main roles of IL-6 is to protect immunocompetence, defined as the ability of a host to respond to infections." (PMID 33244370, 2020). "Accordingly, increased worm burden in IL-6 and NOD2 deficient mice, which showed a delayed neutrophil recruitment to the site of infection in the skin, were overcome by subcutaneous infection, resulting in a worm burden that was comparable to immunocompetent WT animals." (PMID 32107497, 2020).
infection (continued). "Interleukin 6 (IL-6) is a proinflammatory cytokine that is generated by many types of cells and is expressed during states of cellular stress, such as inflammation, infection, wound sites, and cancer." (PMID 32521683, 2020). "The role cold-induced stress has on IL6 expression during bacterial infection adds additional interest to investigate IL6 in the turtle, as infections may be detrimental to the turtle’s welfare—especially during cold periods." (PMID 32466093, 2020). "IL-6 is expressed in the lung in the early response to PR8 infection." (PMID 33193346, 2020). "The gp130 cytokines IL-6, IL-11 and IL-27 differentially affect the outcome of infection with Mtb." (PMID 33334075, 2020). "Interestingly, mouse models of IL6−/− showed reduced neutrophil accumulation at sites of infection or inflammation that seems to be secondary to the effects of IL6 trans-signaling on stromal cells." (PMID 33126846, 2020). "In addition, the TNF and IL-6 protein levels were markedly upregulated in Ppara-/- BMDMs compared with Ppara+/+ BMDMs, at 6 and 18 h after Mabc infection." (PMID 32155958, 2020). "We show that, in contrast to non-typhoid S. Enteritidis infection, S. Gallinarum significantly reduced nitrite ion production and expression of mRNA for heterophil granulocyte chemoattractants CXCLi2 and IL-6 in chicken monocyte-derived macrophages (chMDMs) (p < 0.05) at 6 h post-infection (pi)." (PMID 33076485, 2020). "Although only IL-6 levels significantly decreased in the blood of mice administered with B. animalis alone and the two-bacterium combination on day 5 post-infection, most cytokines displayed an obvious increase in these two groups on day 3 post-infection." (PMID 32345342, 2020). "Il1β, Tnf, Il6, Ccl2, Ccl5, and Cxcl10 mRNAs were all increased in the CNS after infection." (PMID 32047134, 2020). "In our study, linear regressions between the concentration of IL-6 and the number of monocytes in both phases suggest that the activation on macrophages at the site of infection could represent the main source of that cytokine." (PMID 33066100, 2020). "We hypothesized that, initially,there is a peak of pro-inflammatory cytokines, such as IL-6, in the intestinalepithelium that may result in the activation of macrophages and the recruitment ofneutrophils to control infection." (PMID 32725081, 2020). "In addition, proinflammatory cytokines such as TNF-α, IL-1β, IL-6, and IL-8 trigger and rapidly amplify the inflammatory response to limit the spreading of the infection." (PMID 32373312, 2020). "However, the analysis of IFNγ, a product of the adaptive immune response (CD4 and CD8 T cells), showed a trend toward reduced expression in immunized IL-6 KO mice after the lethal infection with influenza virus." (PMID 33193346, 2020). "For example, IL-6 as a lymphocyte stimulating factor was first produced to induce innate and adaptive immune responses in the early infection, but IL-10 is a regulator to alleviate hyper-inflammation for prevention tissues damage in the late infection." (PMID 33044969, 2020). "Moreover, we demonstrated that while IFNAR signaling does not affect the amount of TNF-α produced by BMMCs in response to rVSVΔM51 at 16 h post-infection, IL-6 generation was higher in IFNAR-intact BMMCs compared to IFNAR-blocked and IFNAR−/− BMMCs." (PMID 33261178, 2020). "Moreover, secondary drastic increase of the levels of TNF-α, IL-1β, IL-6, and IL-8, as well as elevated IL-10, was observed at the terminal phase of infection." (PMID 33553280, 2020). "Moreover, genes such as Ifr9, Ifr8, Ifr7, CSF2RA, STAT1, and STAT2 were expressed to a greater extent in the PmQ infection group than PmCQ2, and Il22, Il6, Nos2, Ccl4, Ccl5, Ifr1, Socs1, and Socs3 were increased only in PmQ infected chickens rather than PmCQ2." (PMID 32851030, 2020).
infection (continued). "In the olfactory nervous system, IL-6 likely has important roles with increased IL-6 production reported to occur throughout the primary olfactory nervous system and olfactory bulb after injury and infection, with OECs shown to produce IL-6 in response to S. aureus and B. pseudomallei infection." (PMID 33489937, 2020). "Accordingly, we showed that only CCHFV infection of moDCs induced a significant production of IL-6, IL-10 and TNF-α in comparison to the non-pathogenic HAZV." (PMID 33232320, 2020). "After severe infection, the T Helper (Th) 1 lymphocytes pathway is hyperactivated, causing an excessive production of CD14++ and CD16+ inflammatory monocytes, responsible for inflammatory exacerbation and increased plasmatic concentration of IL-6." (PMID 32635302, 2020). "Systemic inflammation and a cascade of pro-inflammatory cytokines (as demonstrated in part by elevated IL-6) may be a mediator between infection and hypercoagulability and may also destabilize atheromatous plaque." (PMID 32754113, 2020). "Similarly, senescence induced by infection with pks positive E. coli promotes production of reactive oxygen species and secretion of pro-inflammatory cytokines, such as IL6, IL8, monocyte chemotactic protein (MCP)-1 and the matrix metalloproteinase (MMP)-3." (PMID 31973033, 2020). "We observed limited and transient changes in cytokine transcription in monocytes after infection, i.e., a significant increase of IL-6 at 3 hpi and of GM-CSF over the 3 and 6 hpi period, whereas M-CSF was significantly decreased at 9 hpi, with a limited effect of age." (PMID 33121170, 2020). "This hypothesis is also supported by our findings in vitro, which show decreased IL-6 and G-CSF in lung epithelial cells, a key source of inflammatory molecules, after Δmmpl7 mutant infection." (PMID 32695111, 2020). "IL-6, as an important mediator of the acute phase response or as an anti-inflammatory cytokine, is secreted by macrophages to stimulate the immune response during infection." (PMID 32536938, 2020). "Besides the prominent role of interleukin-6 (IL-6) in infection, cancer and inflammation, IL-6 appears to be a cytokine, which mediates an interaction between the immune system and CNS (central nervous system) function." (PMID 32858844, 2020). "At the site of infection, infected cells produce chemokines and cytokines such as type I IFNs, IL-6, IL-8, TNF-α, CCL2 (MCP-1), RANTES, and MIP-1α that recruit immune cells including NK cells, neutrophils, macrophages and DCs to the site of infection where they initiate the innate immune response." (PMID 32375274, 2020). "Also, the infection witnessed an upsurge in pro-inflammatory cytokines and chemokines (IL-6, IL-1β, TNF-α, IFN-γ, and IL-8)." (PMID 33262955, 2020). "Then, we selected IL-6 and adrenaline as targets in a pharmacological approach to further validate the roles of these factors in mediating the mortality of neonatal mice after EV-A71 infection." (PMID 31857694, 2020). "IL-6 is one of the most important cytokines during an infection, along with IL-1 and TNF46." (PMID 33067513, 2020). "IL-6 is well-established biomarker of infection and inflammation during pregnancy." (PMID 32858866, 2020). "Furthermore, Ad14p1 infection of the bronchial epithelial cells resulted in increased expression of IL-6 and the chemoattractant chemokines CXCL10 (IP-10) and CXCL11 compared to infection with Ad5." (PMID 32486177, 2020). "In concert with the pyretic response, TNF-α and IL-6 were elevated in response to infection." (PMID 33306742, 2020). "Indeed, most of the infections can trigger the release of IL-1β from the inflammasome followed by the production of IL-6 that increases the circulating levels of C-reactive protein, the prototypical acute-phase reactant." (PMID 32719685, 2020).
infection (continued). "The shorter terminal half-life of α-IL-6 mAb (T1/2 = 57h) versus α-IL-6R mAb (T1/2 = 223h), possibly due to isotype specific differences in glycosylation may help explain why giving α-IL-6 mAb early after infection provided the most observed clinical benefit." (PMID 33071786, 2020). "These functional SNPs could increase the transcriptional activity of IL-6 and IL-10 promoter, leading to the upregulation of IL-6 and IL-10 in stress or infection." (PMID 32070384, 2020). "Thus, we select IL6 as an inflammatory indicator to clarify the role of AIF1 on CSFV Shimen infection in PAMs 3D4/21 cells." (PMID 32110485, 2020). "Indeed, IL-6 and C-reactive protein, indicators of infection, are elevated in individuals who report long sleep duration." (PMID 32671413, 2020). "Moreover, the antibody-mediated depletion of IL-6 upon i.v. infection with Mycobacterium avium enhances mycobacterial growth." (PMID 33334075, 2020). "While some cytokines/chemokines such as TNFα and MIP-1β peaked very early after H5N1 infection (12 h), others, i.e. IL-1α and RANTES peaked somewhat later (at 30 h), followed by KC (neutrophil-activating protein-3) and IL-6, reaching their peak at 72 h after infection." (PMID 33362782, 2020). "In the innate immune response, IL-6 is produced by myeloid cells [e.g., macrophages and dendritic cells (DCs)] following the recognition of sterile or non-sterile stimuli through toll-like receptors at the site of infection or tissue injury." (PMID 32719685, 2020). "Interestingly, Il1b / Il6 / Irg1 expression increased at 24 hpi after infection in BALB/c macrophages infected with all the strains, except for VFRA." (PMID 32925918, 2020). "To test our hypothesis, we constructed a luciferase-coding plasmid under the control of human IL-6 promoter, namely (-1,000/+11)IL-6-Luc, and tested its response to AdV 7 infection." (PMID 33072092, 2020). "Up-regulation of IL-6 may be also explained by increased fibroblast activity dependent on an ongoing chronic local inflammation possibly initiated by an infection." (PMID 32209102, 2020). "Moreover, we explored the influence of ZAPL and ZAPS on the expression of IFN-β, MxA, TNF, and IL-6 at 12 h after infection." (PMID 32922375, 2020). "The significant processes represent responses to both viral (e.g., defense response to virus) and bacterial (e.g., defense response to bacterium) infection as well as phagocytosis, apoptosis, and pro-inflammatory processes such as IL-6 production, chemotaxis, and complement activation." (PMID 32610501, 2020). "We hypothesized that these lipids may decrease the production of G-CSF, IL-6 and other inflammatory cytokines, thus driving decreased myeloid recruitment and increased iBALT formation upon infection." (PMID 32695111, 2020). "Evidence for the critical role of IL-6 in the acquisition by Mdr2−/− mice of anti-parasite resistance was provided by the reversal of the infection phenotype from parasite blockade in Mdr2−/− C57BL/6 mice to parasite development into blood stage in Mdr2−/− IL-6−/− double knockout mice." (PMID 33329563, 2020). "Furthermore, the expression of TNF, IL-6, and IL-1β mRNA and protein levels were significantly increased in Ppara-/- BMDMs, compared with Ppara+/+ BMDMs, after Mabc infection (protein and mRNA, respectively)." (PMID 32155958, 2020). "While the expression of Cxcl10 and Cxcl11 in C57BL/6 and IL-6−/− mice was similar, it was significantly increased for Cxcl9 in IL-6−/− mice on day 14 and tended to remain higher compared to wild type animals in the further course of infection." (PMID 33375150, 2020). "Since the presence of infection could cause higher biomarker concentrations, especially of CRP, IL-6, PCT, and IPF, the data were analyzed excluding patients who developed infection during the first 3 days after CS." (PMID 37360622, 2020). "During infection, the serum levels of IL-6 can rise to 30–340 pg/mL." (PMID 32316949, 2020).